TSPO (translocator protein)
Diseases named in the same sentence as TSPO in open-access papers (continued):
Sharing a sentence is not in itself a finding about the gene and the disease.
tumor (continued). "However, a role of TSPO in anti-tumor immune response in GB remains unknown so far." (PMID 37158962, 2023). "We have previously shown that uptake of the TSPO-PET tracer, [18F]F-DPA, increases after irradiation in HNSCC cells and tumor xenografts." (PMID 38162485, 2023). "Tumor uptake of both radiopharmaceuticals is more expressed in tumor edge regions, with greater intensity at 2 weeks, as demonstrated by [11C](R)-PK11195 autoradiography and immunofluorescence with TSPO antibodies and CD86 pro-inflammatory phenotype." (PMID 36559209, 2022). "One novel option to demonstrate and monitor post-treatment inflammatory reactions and the immunologic tumor microenvironment (TME) is dual-tracer PET imaging with 18F-FET and 18F-DPA-714 (a ligand of microglial translocator protein (TSPO))." (PMID 35158809, 2022). "In a first pilot study using a third-generation TSPO PET tracer, [18F]GE-180 PET provided a high tumor-to-background ratio (TBR) in untreated and recurrent glioma." (PMID 35804911, 2022). "In MEFs and canine tumor cell lines, TSPO formed a complex with VDAC, protein kinase A (PKA), and ACBD3 in which VDAC1 function was dependent upon TSPO-regulated phosphorylation of VDAC1 by PKA." (PMID 34191248, 2021). "However, this weakness may be justified by the significant proportion of studies in which TSPO PET scan was associated with another radiotracer (e.g. [11C]PIB in Alzheimer, [18F]FET in tumours) hence adding a dosimetry issue for the management of longitudinal studies." (PMID 34387719, 2021). "We found that both TSPO and LAT1 expression was increased in tumor regions of the implanted human or murine GBM cells when compared to the neighboring mouse brain tissue." (PMID 31963507, 2020). "The nuclear localization of TSPO in the U-87MG xenografts but not in cells in culture, therefore suggests that the conditions in the tumor, either in the mouse model or in GBM patients are responsible for inducing TSPO translocation to the nucleus." (PMID 31661894, 2019). "The depletion of hVDAC1 greatly reduced the levels of the multifunctional translocator protein TSPO, which is overexpressed in both the mitochondria and the nucleus of the tumor." (PMID 31661894, 2019). "In some specimens, a very strong TSPO signal was observed in OCT4-negative and AP2G-negative cells, much smaller in size than the tumor cells, likely corresponding to Leydig cells." (PMID 27608010, 2016). "Molecular imaging studies with the TSPO PET ligand [18F]PBR06 revealed selective and targeted uptake not only in engrafted tumor, but infiltrative growth in the opposite hemisphere previously undetected by our T2-weighted MRI scans." (PMID 26517124, 2015). "They showed that TSPO knockdown increased malignancy in vitro, whereas its agonist FGIN‐1‐27 reduced tumor growth in vivo, suggesting that targeting TSPO could be beneficial in CRC treatment." (PMID 40550494, 2025). "In addition, TSPO gene expression levels were analyzed in both CRC tumor and non‐tumor tissues based on gender, age, tumor grade, and cancer stage." (PMID 40550494, 2025). "Overexpression of TSPO inhibits the proliferation of ESCA cells and the formation of tumor clones." (PMID 40936684, 2025). "The precise role of TSPO in CRC remains underexplored, yet emerging evidence suggests that its expression may correlate with tumor aggressiveness and metastatic potential." (PMID 40550494, 2025). "Thus, TSPO expression in CRC appears to be stage‐dependent, with initial upregulation facilitating tumor growth while later downregulation supports survival and metastatic potential." (PMID 40550494, 2025).
tumor (continued). "The expression level of TSPO in tumor tissues was lower compared with the adjacent non-tumor tissues." (PMID 40842566, 2025). "Although direct studies on TSPO in ESCC remain limited, its established involvement in mitochondrial dysfunction and redox regulation indicates that it may also influence tumor progression and therapeutic responses in ESCC." (PMID 40936684, 2025). "Since epithelial‐mesenchymal transition (EMT) contributes to enhanced migration and metastasis of tumor cells, we examined whether the EMT process could be mediated by TSPO." (PMID 36994647, 2023). "Furthermore, TSPO expression positively correlated with PD-L1 (CD274), which is induced in response to the activity of tumor-infiltrating T cells in various tumors." (PMID 37158962, 2023). "Since TSPO exerted its tumor protective role through selective protection against TRAIL in vitro, we speculated whether TSPO expression might correlate with TRAIL receptor expression in primary GB." (PMID 37158962, 2023). "The combination of multiple boron compounds is thought to be a means of resolving this issue, and this basic study demonstrates the utility of the simultaneous use of TSPO-targeted boron compound (DPA-BSTPG) and BPA, which target tumor tissue by different mechanisms." (PMID 36831378, 2023). "18F-DPA-714 uptake is doubled in the presence of TSPO expressing DIPG cells, as highlighted by the significant rise of the pons to striatum AUC ratios of the tumor-bearing rats (AUCr = 2.03 ± 0.22 for tumor-bearing rats versus 1.55 ± 0.24 for sham rats; p-value = 0.02)." (PMID 36293329, 2022). "TSPO protein expression was also measured from non-irradiated and irradiated FaDu tumours by Western blot and IHC 1 and 2 weeks after RT." (PMID 33340054, 2021). "Western blots revealed increased, but variable, TSPO protein levels after RT compared to non-irradiated tumours." (PMID 33340054, 2021). "While LAT1 is mainly expressed in tumor cells, we and others have found that TSPO is expressed not only by tumor cells, but additionally in microglia/macrophages, endothelial cells, and pericytes of the tumor microenvironment." (PMID 31963507, 2020). "TSPO was identified as a key target gene of CDK2, and CDK2 may be involved in tumor progression via the regulation of the interaction of TSPO and CDK1." (PMID 33066460, 2020). "We speculated that [18F]DPA714, a specific TSPO tracer, may monitor BAT activity in tumor-bearing mice in vivo." (PMID 32902340, 2020). "Interestingly, we found TSPO expression in CD31-positive endothelial cells, as well as in PDGFRB-positive pericytes attached to the newly forming vasculature within the tumor region." (PMID 31963507, 2020). "Tissue examination revealed that GAMs failed to express TSPO, although both tumours contained a substantial number of microglia." (PMID 27077069, 2016). "TSPO did not directly correlate to the tumour growth rate, metastatic potential or drug responsiveness." (PMID 27077069, 2016). "Interestingly, TSPO was expressed in OCT4- and AP2G-positive cells, where it was localized in the cytoplasmic compartment, forming a ring around tumor cell nuclei, while the two transcription factors presented nuclear stainings." (PMID 27608010, 2016). "No data are available on the extent of microglial TSPO density in the tissue distant from the tumour epicentre." (PMID 27077069, 2016). "[11C]PK11195 exhibited relatively modest increased uptake in tumor tissue compared to normal brain, despite large differences in relative TSPO expression and high levels of non-displaceable ligand binding." (PMID 26517124, 2015). "Nevertheless, limited available data suggest that the impact of TSPO expression in some tumor types may not prove problematic for M2 imaging." (PMID 40725764, 2025).
tumor (continued). "Most importantly, higher TSPO-PET signals of the contralateral hemisphere were observed in patients with persisting epileptic seizures and associated with shorter overall survival independent of the tumor phenotype." (PMID 39150564, 2024). "Even though tumors repeatedly showed a tendency to grow vertically along the IC, which thus does not correspond to a natural growth situation, increased uptake well above the superior tumor margin was noted in all cases, here pointing towards a non-tumoral origin of increased TSPO expression." (PMID 38255293, 2024). "However, compartment modeling of 33 demonstrated a greater tumor-to-background ratio, a higher tumor BP and a lower brain BPND with respect to 28 and 32, thus suggesting 33 as a better candidate for imaging tumors with low TSPO expression." (PMID 39275061, 2024). "Thus, after tumor cell inoculation, the level of tumor cell-related TSPO expression can be monitored without interfering signal from endogenously TSPO-expressing macrophages, microglia, activated astrocytes or other cells of the host." (PMID 35453488, 2022). "We investigated 18F-DPA-714, a TSPO PET radioligand used in many clinical trials, as a potential biomarker evaluating the extent of DIPG tumors in a patient-derived orthotopic xenograft (PDOX) rat model established with HSJD-DIPG-007 primary DIPG human tumor cells." (PMID 36293329, 2022). "Targeting MDM2/TPSO (translocator protein), MDM2/PKC (protein kinase C), MDM2/NF-kB (nuclear factor-kappa B), MDM2/Bcl-2 (B-cell lymphoma-2) and MDM2/NFAT1 (nuclear factor of activated T-cells 1) had good anti-tumor activity and had the potential to reduce the adverse reactions of MDM2 inhibitors." (PMID 35831864, 2022). "Our hypothesis is that there is overexpression of TSPO due to tumor development and inflammatory infiltrate, not necessarily correlated with increased uptake of [18F]FDG." (PMID 36559209, 2022). "TSPO-PET tracers have not comprehensively been evaluated in peripherally located tumours." (PMID 33340054, 2021). "Compared to non-irradiated tumours, the TSPO protein expression varied greatly after RT." (PMID 33340054, 2021). "Therefore, the combination of FET-PET and TSPO-PET might be a promising way to visualize not only the tumor, but also the reactive tumor microenvironment, such as the tumor-infiltrating myeloid cells and the tumor neo-vasculature." (PMID 31963507, 2020). "In addition to MRI, 18-kDa mitochondrial translocator protein (TSPO) Positron Emission Tomography (PET) imaging has also been reported to be a useful marker of tumor and immune cells in glioblastoma, even outside the contrast-enhancing region of the tumor on MRI16." (PMID 41266763, 2025). "However, the inclusion of various additional tumor models in in vivo imaging studies will be of interest, as different molecularly defined subtypes of GBM may show different levels of TSPO expression, and TSPO-targeted PET imaging might therefore be useful to non-invasively assess the latter." (PMID 35453488, 2022). "However, a concomitant neuroinflammatory response in brain regions without tumor infiltration could potentially affect TSPO-PET binding in the contralateral pseudo-reference tissue." (PMID 34073557, 2021). "The first-generation TSPO-targeting radioligand [11C]-(R)PK11195 has been extensively researched for inflammation and tumor imaging, despite its low tumor-to-background ratio and lack of specificity." (PMID 35788730, 2022). "We generated STAR knockout (KO) MA-10 mouse tumor Leydig cells and showed that STAR KO cells failed to form progesterone in response to dibutyryl-cAMP and to TSPO drug ligands, but not to 22(R)-hydroxycholesterol, which is a membrane-permeable intermediate of the CYP11A1 reaction." (PMID 33670702, 2021).
tumor (continued). "Similar to 18F-FDG PET/CT imaging, the fact that TSPO and FRβ are also expressed on various cancer cells to a variable degree may limit their usefulness as a targets for TAM imaging in tumors, although this may not be the case for all tumor types." (PMID 40725764, 2025).
cancer (80 papers, 2009 to 2026). A tumor composed of atypical neoplastic, often pleomorphic cells that invade other tissues. "Second, while key pathways associated with TSPO and cancer stemness were identified, direct experimental validation is lacking." (PMID 40936684, 2025). "Among the genes identified in our model, TSPO (translocator protein) has emerged as a significant mitochondrial biomarker implicated in cancer biology." (PMID 40936684, 2025). "Generally speaking, high levels of TSPO in malignant tumors were found to be associated with a worse prognosis." (PMID 38675106, 2024). "TSPO has previously been reported to be overexpressed as well as associated with poor survival in several cancer types." (PMID 38162485, 2023). "In oropharyngeal cancer OS showed a significant (p = 0.011) association between lower TSPO expression and worse survival." (PMID 38162485, 2023). "The overexpression of the mitochondrial translocator protein (TSPO) is linked to several pathological conditions like neuropathic pain, cancer, and traumatic brain injury." (PMID 37582750, 2023). "Herein, we review recent evidence and the mechanisms of TSPO in the development of chronic pain associated with peripheral nerve injury, spinal cord injury, cancer, and inflammatory responses." (PMID 36071748, 2022). "Overexpression of TSPO is associated with several diseases, such as neurodegenerative diseases, neuroinflammation, brain injury, and cancers." (PMID 36432736, 2022). "TSPO overexpression is also associated with several tumors, including breast and colon cancers, and it is considered a cancer biomarker." (PMID 36432736, 2022). "More recently, TSPO PET imaging has been shown to assume a promising involvement in the development of diagnostic strategies in cancer." (PMID 29887768, 2018). "Chronic inflammation of the gastrointestinal tract increasing the risk of cancer has been described to be linked to the high expression of the mitochondrial translocator protein (18 kDa; TSPO)." (PMID 27054921, 2016). "Despite the extensive screening of TSPO in cancer types outside the CNS and the association of high TSPO with disease progression and diminished survival, TSPO in brain metastases from solid cancer is still unexplored territory." (PMID 27077069, 2016). "Many radioligands have been explored for imaging the 18-kDa translocator protein (TSPO), a diagnostic and therapeutic target for inflammation and cancer." (PMID 26194010, 2016). "The downregulation of TSPO in later stages may be associated with cancer cell adaptation to low‐oxygen environments, decreased apoptosis susceptibility, and a transition to mesenchymal‐like states that favor invasion and metastasis." (PMID 40550494, 2025). "In addition, there was a definite association between the level of aggressivity of cancer and the levels of TSPO in these cancer cells; this suggests that levels of TSPO can be a good indicator of an aggressive phenotype in several cancers." (PMID 38675106, 2024). "Previous studies described the association between TSPO and cancer." (PMID 34063262, 2021). "High expression of TSPO is associated with invasiveness in several cancers including GBM." (PMID 33066460, 2020). "The TSPO has been widely studied in glioma cell lines, but it is still unclear whether this molecule has causative or contributory role in tumorigenesis or whether up-regulation represents an epiphenomenon accompanying cancer." (PMID 27077069, 2016). "Several salivary proteins have been investigated as potential biomarkers in human cancers, including oral cancer; among them is the mitochondrial translocator protein (18 kDa), or TSPO—previously known as the peripheral benzodiazepine receptor (PBR)." (PMID 40961028, 2025). "Our analysis also highlights that higher TSPO expression correlates with shorter overall survival and progression‐free survival, particularly in aggressive cancer types." (PMID 40550494, 2025).